SDC1 (syndecan 1)
Diseases named in the same sentence as SDC1 in open-access papers (continued):
Sharing a sentence is not in itself a finding about the gene and the disease.
tumor (continued). "The high expression of SDC1 and SDC4 indicates proliferation, metastasis and drug resistance of tumor cells, which will result in a poor prognosis." (PMID 35127731, 2021). "In SMM a multi-peptide vaccine PVX-140 has been designed to induce a T cell mediated immune response by specifically stimulating CTLs with the tumor antigen targets X-box binding protein 1 (XBP1), Syndecan-1 (CD138), and SLAMF7 (CS1)." (PMID 32432039, 2020). "The cell surface proteoglycan Sdc-1 acts as an ECM adhesion receptor and co-receptor for numerous signaling pathways with relevance to tumor progression." (PMID 32477959, 2020). "In the tumor sample inoculated with shLuc-transfected cells, several vascular cavities were seen with positive CD31, ANPEP, SDC1, and integrin β4 immunostainings." (PMID 32756007, 2020). "Shed syndecan-1 ectodomain was shown to capture VEGF and form a complex that activates integrin and VEGF receptors on adjacent endothelial cells thereby stimulating tumor angiogenesis." (PMID 31963505, 2020). "Syndecan-1-expressing fibroblasts reorganize the ECM promoting adhesion and directional movements of tumor cells during migration." (PMID 32388727, 2020). "There was a clear trend of increasing gene expression levels of MET, MELK, SDC1 and TOP2A in primary tumor compared to normal samples." (PMID 31412643, 2019). "Syndecan-1 (CD138), MUC-1 (CD227) CD45, CD34, and the putative cancer stem cell markers CD15, CD24, CD44, and CD133 surface expression were evaluated on CSF floating tumor cells." (PMID 28399903, 2017). "MMP7 and MMP9 induced syndecan 1 and CXCL6 production in tumor cells, which act as chemoattractants for neutrophils and mediate their influx to the tumor microenvironment." (PMID 26956475, 2016). "In contrast to the changes of syndecan-1 in serum, syndecan-1 was significantly downregulated in HCC tumor, its expression in thirteen cases (32.5%) was approximately two-fold lower in HCC tumor, compared with corresponding NTs." (PMID 27556509, 2016). "In vitro studies have shown that stromal cells isolated from both breast and pancreatic tumors can create increasingly aligned fibronectin matrices in a syndecan-1 or FAP-dependent manner respectively, which facilitate tumor cell motility." (PMID 26716418, 2016). "Most probably, the phenomenon described here, i.e. SDC1 overexpression in irradiation-mediated senescent fibroblasts due to TGF-β action, is the combined outcome of the tumor promoting effects of these two factors." (PMID 27434331, 2016). "Moreover, we focus on the cellular localization of this proteoglycan as cell membrane anchored and/or shed, soluble syndecan-1 with stromal or nuclear accumulation and how this may carry different, highly tissue specific prognostic information for individual tumor types." (PMID 26420915, 2015). "Besides this, syndecan-1 may also be regarded as a target for the treatment of some tumor types." (PMID 26378057, 2015). "Then, the “loaded” with growth factors shed SDC-1 binds to ECM macromolecules, such as FN and collagen, rendering these growth factors available in the tumor microenvironment even in distal sites." (PMID 24551591, 2014). "Cytoplasmic expression of SDC1 is positively correlated with tumor-prone proteins (WT1 and WNT1) and membranous expression of SDC1 is positively correlated with the tumor suppressor (P16)." (PMID 24373193, 2013). "High level of heparanase implies low levels of nuclear syndecan-1 and increased histon acetyl transferase (HAT) activity leading to enhanced transcription of VEGF and MMP-9, both known to drive an aggressive tumor phenotype." (PMID 24392351, 2013).
tumor (continued). "As such, HRS cells that harbor the FGF2+/SDC1+ immunophenotype and express both MMP9 and TGFβ1 are the cells most likely to be shed from the tumor microenvironment." (PMID 23988031, 2013). "This study demonstrated that serum syndecan-1 levels are significantly elevated in patients with HCC, and this elevation correlates with advanced stage (BCLC) of the tumor." (PMID 22396913, 2012). "Tumor progression depends on crosstalk between tumor cells and stromal fibroblasts and it has lately become evident that the stromal-derived HSPG syndecan-1 is important in signaling between stromal fibroblasts and carcinoma cells." (PMID 22848466, 2012). "Immunohistochemically, tumor cells were positive for HMB45, Melan A, S100 protein, and only focally for CD138/syndecan-1." (PMID 23133774, 2012). "Several membrane PGs, including SDC-1, SDC-4, NRP-1, and CSPG4 can potentially present GAG chains on the surface of tumor cells." (PMID 21658254, 2011). "Here we investigate the sub-cellular distribution of syndecan-1, FGF-2, FGFR-1 and heparanase in malignant mesenchymal tumor cells, and explore the possibility of their coordinated translocation to the nucleus." (PMID 19802384, 2009). "Similarly, syndecan-1 (SDC1) restrained IFN-γ-STAT1 signaling and antigen presentation in tumor cells and thereby attenuated the sensitivity to T cell-mediated cytotoxicity and induced immunotherapy resistance." (PMID 40524231, 2025). "Thus, our data strongly support that the signaling coming from the TME and converging on SDC1 and SDC4 on START tumor cells sustain tumor progression." (PMID 38546390, 2024). "Additionally, Midkine (MDK) released from tumour cells interacted with SDC4, SDC1, NCL, ITGA4, ITGA6 and ITGB1 on immune cluster." (PMID 39187937, 2024). "Additionally, promising therapies to reduce its elimination to limit tumor progression include heparanase and MMP inhibition, synthetic proteoglycans mimicking SDC1, and strategies targeting growth factor interactions." (PMID 39728992, 2024). "Of the 47 cases, 30 (64%) were positive for syndecan-1 expression in tumor cells, while 17 (36%) were negative." (PMID 39728992, 2024). "Additionally, TENASCIN was frequently observed in the HAS group, with tumor cells in this group interacting with other cells, including tumor cells themselves, via TNC - SDC1/SDC4 or TNC - ITGA8_ITGB1/ITGAV_ITGB6." (PMID 39267750, 2024). "The patients with positive expression of SDC1 in tumor cells had poor prognosis and low frequencies of TILs, while patients with negative expression of SDC1 in CAFs had poor prognosis and high frequencies of TILs." (PMID 37069585, 2023). "The patients with positive expression of SDC1 in tumor cells had significantly lower DFS compared to patients with negative SDC1 expression in tumor cells (p < 0.001)." (PMID 37069585, 2023). "Syndecan 1 (SDC1) is a transmembrane heparan sulfate proteoglycan component that has a variety of functions in the development, proliferation, adhesion, and angiogenesis of tumor cells." (PMID 38048216, 2023). "Finally, we found that after inhibiting SDC1 and ITGA2 expression in BxPC-3 and MIA-PaCa2 cell lines, the tumor size was significantly reduced, showing a potential therapeutic effect." (PMID 37907515, 2023). "Both syndecan-1 and CD20 expression were correlated with tumor grade." (PMID 37370735, 2023). "Thereafter, we inoculated BxPC-3 and MIA-PaCa2 cell lines into immunodeficient mice to construct a mouse tumorigenic model, and detected the transcription levels of SDC1 and ITGA2, by qRT-PCR, in tumor tissues on the fifth and tenth days after tumorigenesis by qRT-PCR." (PMID 37907515, 2023).
tumor (continued). "Indeed, multiplex immunofluorescence experiments were also performed and validated the increased colocalisation of SDC1 and COL4A1 in the recurrent group, mainly in the tumour region." (PMID 37488671, 2023). "Concerning the correlation between syndecan-1 levels and the tumor stage, the correlation was not statistically significant." (PMID 38022112, 2023). "The carriers of ofCS are syndecan 1 (SDC1) and chondroitin sulfate proteoglycan 4 (CSPG4), proteoglycans that are highly expressed in BC and thus increase the overall amount of ofCS in the tumor." (PMID 37110670, 2023). "In contrast, 7 out of 15 proteins including, IL17B (P = 0.0001), IP10 (P = 0.0135), LOX-1 (P < 0.0001), MIG (P < 0.0001), MIP-1d (P < 0.0001), SDC1 (P < 0.0001) and OPN (P < 0.0001) were significantly upregulated in tumour tissues compared to normal (AN and PN)." (PMID 34997107, 2022). "In particular, based on high level of SDC1, TNFRSF17, MZB1, CD38 and low level of CD19 and MS4A1, Cluster 0, Cluster 1 and Cluster 12 were defined as SDC1+ cells, namely plasma cell in HD controls and tumor cells in MM patient." (PMID 36532059, 2022). "SDC1 silencing inhibits the organization of tumor ECs into patent vessels in severe combined immunodeficient (SCID) mice, reduces membrane expression of VEGFR2, and thus weakens the colocalization of VEGFR2 with SDC1." (PMID 36358833, 2022). "SDC1 might regulate tumor cell immune invasion in the TME and even help tumor cells escape immune surveillance." (PMID 35669186, 2022). "In addition, HPSE cleaves HS chains on syndecan-1, and a tight relationship between HPSE and syndecan-1 has been documented in tumor and non-tumor models." (PMID 35965510, 2022). "Methods that directly interfere with sheddase access to cleavages sites or stabilize the SDC-1 core protein into a confirmation less prone to proteolysis may also be good strategies to control SDC-1 shedding and subsequent tumor progression." (PMID 35118073, 2021). "Frequently, but not always, syndecan-1 levels decrease as tumor grade, stage and invasiveness and dedifferentiation increase." (PMID 33921767, 2021). "This would indicate that syndecan-1 shedding, presumably from the tumor and/or stroma has negative connotations." (PMID 33921767, 2021). "The source of syndecan-1 expression in tumor stroma is not clear and accordingly various probabilities have been raised." (PMID 31540870, 2021). "In primary carcinomas, syndecan-1 did not correlate with tumor size ρ = 0.14 (p = 0.835), grading ρ = 0.063 (p = 0.187), or GPT-value (ρ = 0.49 (p = 0.714))." (PMID 34206469, 2021). "SDC-1 acts as a co-receptor for a wide range of extracellular ligands, including VEGF, a key signaling molecule in angiogenesis both during embryogenesis and tumor growth." (PMID 33562126, 2021). "Heparanase can be used to regulate Sdc-1 levels in the nucleus; however, removal of HS from the nucleus by nuclear heparanase promotes an aggressive tumourigenic phenotype by enhancing HAT activity, which elevates the expression of tumour-promoting genes." (PMID 33922532, 2021). "Expression of SDC1 in normal prostate tissues (non-neoplastic tissue adjacent to the tumor), when positive, showed strong immunostaining in the basal cells of the epithelium and around the smooth muscle cells of the stroma and blood vessels." (PMID 34445387, 2021). "The Sdc-1 heparan sulfate chains serve as substrates for HPSE, and this degradative process modulates tumor angiogenesis, growth factor-dependent tumor cell proliferation and metastatic behavior in a variety of tumor entities." (PMID 32477959, 2020). "A follow up study showed that the tumor resistance conferred by the absence of syndecan-1 extended beyond the mammary glands in null mice and was a multi-organ effect." (PMID 33330458, 2020). "With more advanced tumor stage the level of syndecan-1 proved to be higher, however, the difference did not proved to be significant (data not shown)." (PMID 30826971, 2020).
tumor (continued). "In this context, MMP-7 expression has been inversely correlated to syndecan-1 abundance, indicating a role of MMP-7 in shedding the protein, a function which is beneficial for wound healing but harmful with respect to tumor progression." (PMID 32796709, 2020). "In CRC cells, aberrant expression of E-cadherin/β-catenin complex can be observed as well as that of other angiogenesis markers such as Syndecan-1, platelet (Endothelial) cell adhesion molecule 1 [P(E)CAM-1, CD31], and endoglin (CD105), all involved in tumor progression and prognosis." (PMID 33276489, 2020). "In addition to the change of tumor volume, tumor metastasis was also affected by the interaction between SCGB3A2 and SDC1." (PMID 31616642, 2019). "SDC1 expression was not correlated with age (p = 0.345), sex (p = 0.686), or tumor diameter (p = 0.232)." (PMID 31182980, 2019). "Our in vitro data also showed that tumor Sdc-1 silencing did not significantly alter the proportion of the Th2 (IL4+CD4+) subset among CD4+ T cells of non-IBC patients under indirect and direct co-culture conditions." (PMID 31145753, 2019). "Furthermore, elevated levels of VEGF and shed SDC1 form matrix-anchored complexes that together activate integrin and VEGF receptors on endothelial cells, thereby stimulating tumor angiogenesis." (PMID 31443604, 2019). "Furthermore, CSF-1/CSF-1R also showed a higher correlation with tumor infiltrating lymphocytes (TILs) than IL-34, PTPRZ1, and syndecan-1." (PMID 29796177, 2018). "In summary, apart from insignificantly smaller tumor size in Sdc1−/− animals, no Sdc1-related differences were identified in the primary 4T1 mammary fat pad tumors." (PMID 29976229, 2018). "Although our results point to an Sdc1 effect on metastatic outgrowth, we cannot rule out the possibility that host Sdc1 levels affect tumor cell extravasation." (PMID 29976229, 2018). "The axillary node metastases from the IDC demonstrated a negative relationship between the Sdc1 expressed in the tumor epithelium and the patient age (P = 0.043), as well as the ER (P = 0.038) and PR expression (P = 0.010) in the primary tumors." (PMID 30151336, 2018). "The Ki67 proliferation index and the rate of apoptosis of the metastatic tumor cells were diminished in Sdc1−/− vs. Sdc1+/+ animals, and leucocyte density was indistinguishable." (PMID 29976229, 2018). "The positive correlation between the Sdc1 expression in the stroma of the metastases and the number of the primary tumor foci (P = 0.022) was significant, as well as the negative correlation with the PR expression (P = 0.032) in the primary tumors." (PMID 30151336, 2018). "The soluble ectodomain of syndecan-1 binds several matrix effectors (e.g., VEGF, FGF-2, or cytokines) and presents them to the corresponding cell surface receptors promoting angiogenesis and tumor growth." (PMID 30619269, 2018). "Sdc1 modulates tumor progression not only by cell autonomous but also by cell non-autonomous mechanisms." (PMID 29976229, 2018). "Elevated SDC1 levels were correlated with more advanced tumor grades in both datasets (Kruskal-Wallis non-parametric test, p<0.0001 for both)." (PMID 28422726, 2017). "As expected, no Sdc1 expression was detected in normal / tumor tissue samples derived from Sdc1-KO mice." (PMID 28350804, 2017). "Forty pairs of HCC tumor and adjacent non-tumorous (NTs) tissues were collected to assess the relationship between S1P receptors and syndecan-1 in HCC." (PMID 27556509, 2016). "Indirect interactions between syndecan-1 and integrins have also been described, such as the one between α6β4 integrin and syndecan-1, an interaction mediated by human epidermal growth factor receptor 2 (HER2) that leads to tumor cell survival in vitro." (PMID 26558271, 2015). "Furthermore, elevated levels of VEGF and shed Syndecan-1 form matrix-anchored complexes that together activate integrin and VEGF receptors on endothelial cells, thereby stimulating tumor angiogenesis." (PMID 26460958, 2015).
tumor (continued). "Tumor grade was found to be related to the proportion of SDC1-positive cells, rather than to the intensity of SDC1 staining." (PMID 26293675, 2015). "Further investigation of the underlying mechanism indicated that SDC-1 and FGF-2, but not FGFR-1, share a common transport route and co-localize with heparanase in the nucleus at mesenchymal tumor cells." (PMID 24551591, 2014). "These increases suggest that a large tumor macrophage population promotes poor clinical outcome by potentiating aggressive CD30+ tumor cells in a subset of HL patients, and some of these CD30+ cells may express FGF2 and SDC1." (PMID 23988031, 2013). "As far as we know, all previous studies on SDC1 expression in tumor cells by immunohistochemistry do not differentiate the locations (the cytoplasmic membrane or the cytoplasm) of SDC1 expression." (PMID 24373193, 2013). "The effects of shed syndecan-1 in the stroma is in majority of tumor types in contrast to those of cell-surface syndecan-1, the abundance of syndecan-1 in the tumor stroma being a negative prognostic factor and it correlates to a more aggressive phenotype." (PMID 24392351, 2013). "Although the presence or absence of the ectodomain did not influence the proliferation enhancing effect of syndecan-1 in cell culture, in our mouse model the FullEGFP transfected tumours grew faster than the 78Sig expressors." (PMID 22745764, 2012). "Based on our in vitro results, we conclude that the tumour promoter role of syndecan-1 observed in HT-1080 cells is independent of its ectodomain; however, in vivo the presence of the ectodomain further increases tumour proliferation." (PMID 22745764, 2012). "Similarly, WWP1, SDC1 (syndecan 1), EZH2, CCND1, ADAM9 and MEMO1 have oncogenic activities and are targeted by the potentially tumor suppressor miRNA miR-195, miR-10b, let-7c, miR-17 and miR-125b." (PMID 21375733, 2011). "Information on syndecan-1 involvement in mesenchymal tumor cell adhesion and migration is still lacking, especially with regard to the specific contribution of its distinct functional domains." (PMID 21731601, 2011). "Nevertheless, from the current analysis, the presence of stromal syndecan-1 did not correlate with a more biologically aggressive tumor phenotype or altered patient survival outcomes." (PMID 18590537, 2008). "In contrast to the normal stroma that was typically negative for syndecan-1, some tumor specimens, without or with tumor expression of syndecan-1, had positive staining for syndecan-1 in the stroma." (PMID 18590537, 2008). "Thus, a novel pathwaylinking n-3 PUFAs to apoptosis in tumor cells is as follows: DHA activates PPARγ, which results in transcriptionalupregulation of the syndecan-1 target gene, and the syndecan-1 protein inducesapoptosis." (PMID 18769551, 2008). "In 87% of adenocarcinomas, syndecan-1 was decreased or absent; only 13% of patients had stained for syndecan-1 on more than 75% of tumor cells." (PMID 18590537, 2008). "Furthermore, syndecan-1 was reported to regulate metabolic reprogramming and glucose metabolism, extending its role to not only ECM modulation, but also the metabolic adaptation of tumour cells." (PMID 41463344, 2025). "Additionally, fibroblasts expressing a mutant SDC1 (without HS chains) are not able to stimulate tumor growth." (PMID 36980680, 2023). "Disruption of the complex in HNSCC cells in vitro with a peptide mimetic of the organizer site in Sdc1 (called SSTNIGF1R) inactivates IGF1R, even in the presence of IGF1, and relieves the suppression of apoptosis signal-regulating kinase-1 (ASK1), dramatically reducing tumor cell survival." (PMID 36968227, 2023). "Furthermore, the gene expression levels of COL1A1 with SDC1, COL1A2 with SDC1, and COL6A3 with SDC1 were significantly positively correlated in TCGA-BC and TCGA-PDAC, supporting their potential interaction in the surrounding tumor niche." (PMID 38002057, 2023).